RN7SL814P (RNA, 7SL, cytoplasmic 814, pseudogene)
Gene: Miscellaneous RNA gene on chromosome 5 (74,317,986 to 74,318,285, forward strand). Ensembl gene ENSG00000244326.
Homologues: Orthologues: macaque Metazoa_SRP (92% identical), chimpanzee Metazoa_SRP (89% identical). Paralogues in human: RN7SL1 (84% identical), RN7SL2 (84% identical), RN7SL3 (83% identical), RN7SL444P (81% identical), RN7SL296P (81% identical), RN7SL783P (81% identical), RN7SL220P (80% identical), RN7SL493P (80% identical), RN7SL797P (80% identical), RN7SL126P (80% identical), RN7SL480P (80% identical), RN7SL543P (80% identical), and 701 more.